CTLA4 (cytotoxic T-lymphocyte associated protein 4)
Diseases named in the same sentence as CTLA4 in open-access papers (continued):
Sharing a sentence is not in itself a finding about the gene and the disease.
cancer (continued). "More recently, CTLA-4 blockade has been demonstrated to be a curative strategy for cancer therapy through the challenge with the CD28-B7 combination to exhibit an inhibitory effect on signaling molecules in a variety of cancer diseases." (PMID 32580338, 2020). "Moreover, antibodies targeting cytotoxic T-lymphocyte antigen (CTLA)-4 have been successfully used as cancer immunotherapy; the anticancer activity of CTLA-4 depends on intestinal flora." (PMID 33537234, 2020). "Finally, memory Th1 and Tc1 immune responses directed against immunogenic bacteria E. hirae, A. muciniphila, and B. fragilis dictated progression free survival in cancer patients treated with anti-PD-1 or anti-CTLA-4 Abs." (PMID 33381121, 2020). "The field of cancer immunotherapy has grown expansively in recent years to include the therapeutic use of cancer vaccinations, chimeric antigen receptor T-cell therapy, and agents that block immune checkpoint receptors and/or ligand interactions such as CTLA-4 and PD-1." (PMID 32859926, 2020). "As a result, the blockade of CTLA-4 or inhibiting CD39 activity could potentially help in the treatment of these types of cancer." (PMID 33519807, 2020). "By blocking CTLA-4 or PD-1 function, the host immune response against cancer cells is enhanced." (PMID 32290812, 2020). "Consequently, multiple clinical trials of NKTR-214 in combination with anti-PD-1, anti-CTLA-4, or other agents in multiple cancer histologies are currently underway (e.g., NCT02983045, NCT03138889, NCT03435640, NCT03635983)." (PMID 32005826, 2020). "Specifically, due to existing experience combined with proven efficacy in other cancers and diseases, IL-6 and the immune checkpoint inhibitors (anti-PD-1/PD-L1 and anti-CTLA-4) may represent particularly good targets/therapies." (PMID 32075140, 2020). "Recently, abnormal expression of CTLA-4 gene has been documented in many types of cancers, and it might contribute to cancer initiation and progression." (PMID 32178688, 2020). "Most of the studies so far have focused on the CTLA-4 and PD-1/PD-L1 axis of cancer immunotherapy, but novel immunotherapeutic targets such as co-inhibitory molecules LAG-3 or TIM-3 or co-stimulatory molecules such as OX40 and GITR are currently being explored in mice models and clinical trials." (PMID 32793500, 2020). "The CTLA-4 is a surface molecule expressed by activated T cells, inhibition of CTLA-4 may increase the regulation of the immune response to cancer cells." (PMID 33362722, 2020). "The success of novel immune modulators, such as inhibitors of cytotoxic T-lymphocyte antigen-4 (CTLA-4) and programmed death ligand-1 (PD-L1), in treating certain types of cancers, has recently led to the emergence of ‘immuno radio-oncology’ as a new field of research." (PMID 30911090, 2019). "Finally, we applied the Ion Torrent-based approach to evaluate clonality and convergence in a cohort of individuals receiving anti-CTLA-4 blockade for cancer." (PMID 31993050, 2019). "Indeed, antibodies against CTLA-4 (i.e., Ipilimumab) or PD-1/PD-L1 (i.e., Nivolumab, Pembrolizumab, and Atezolizumab) demonstrated a relevant clinical value in different cancer patients." (PMID 31179334, 2019). "Such lysates may be suitable “cancer-immunotherapy enhancers” for CTLA-4 Ab, both owing to their inhibition of the growth of abnormal bacteria in CRC mice and synergy with the Toll-like receptor (TLR) signaling pathway." (PMID 31882868, 2019). "In contrast, blockade of the CTLA-4 pathway may show the potential for the development of new therapies against chronic infectious diseases and cancers." (PMID 31665022, 2019). "In contrast, CTLA4 is highly expressed in both subtypes of cancer, suggesting that therapies targeting CTLA4 and its ligands may be beneficial for both subtypes." (PMID 30655605, 2019). "Other immune checkpoint inhibitors (such as anti-CTLA4, mTORC1/2 inhibitors) used primarily to treat cancer might also be of value in reducing HIV reservoirs and persistence." (PMID 31921023, 2019).
cancer (continued). "It remains unclear why the clinically used anti-CTLA-4 antibodies, popularly called checkpoint inhibitors, have severe immunotherapy-related adverse effects (irAEs) and yet suboptimal cancer immunotherapeutic effects (CITE)." (PMID 31267017, 2019). "Among the checkpoints, cytotoxic T-lymphocyte-associated protein 4 (CTLA-4) and programmed cell death protein 1 (PD-1) have been found to be the most reliable targets and drugs targeting CTLA-4 and PD-1 drastically changed the outcomes of treatment for advanced cancers." (PMID 31196207, 2019). "In addition, introducing immune checkpoint inhibitors, such as anti-cytotoxic T-lymphocyte-associated antigen 4 (anti-CTLA4), and cancer-targeted vaccines have expedited the field of therapeutic anticancer approach by boosting anticancer immune functions." (PMID 30691225, 2019). "It is still debated whether CTLA-4 blocking antibodies deplete intratumoral Tregs in cancer patients." (PMID 30975201, 2019). "In this study, CTLA-4 expression in either cancer cells or TIICs was associated with shortened overall survival (OS) in ESCC patients, and the OS of patients with CTLA-4-positive epithelial cells was similar to that of patients with CTLA-4-positive TIICs." (PMID 31771653, 2019). "Anti-CTLA-4 antibodies have been observed in mouse models of cancer to deplete T-reg cells by ADCC, a function that relies on specific antibody isotypes engaging with FcγR on effector cells (monocytes, macrophages, NK cells) that are cytotoxic to T-regs within the TME." (PMID 30941125, 2019). "PD-1-blocking antibodies, either as monotherapy or in combination with other compounds, have been used to enhance anti-tumor immunity in several cancer types with an acceptable safety profile and together with antibodies targeting CTLA-4 have revolutionized cancer treatment." (PMID 31754127, 2019). "In addition, one limitation of using anti-CTLA-4 for a variety of cancers in the clinic is its toxicity." (PMID 31804466, 2019). "Moreover, compared with monotherapy, the combined use of anti-CTLA-4 and anti-PD-1 has demonstrated prolonged progression-free survival and significant tumor regression in clinical trials of cancer patients." (PMID 31379886, 2019). "To comprehensively investigate the immunoinhibitory pathways in T cells, we used FACS to analyze the surface expression of eight IRs (PD-1, Tim-3, BTLA, KLRG-1, TIGIT, 2B4, CD160, and CTLA-4) on T cells from peripheral blood and tumors isolated from 131 cancer patients." (PMID 31709176, 2019). "CTLA–4 is constitutively expressed in regulatory T cells and is upregulated in conventional T cells after the phenomenon of activation, which is considerable in cancer." (PMID 31137683, 2019). "Despite the low response rates and immune-related adverse events in some cancer patients, both CTLA4 and PD-1/PD-L1 inhibitors have broadly demonstrated their value to boost potent and durable anti-tumor responses and to increase the average life expectancy for metastatic cancer patients." (PMID 31756919, 2019). "ICI treatments thus represent a major advance in cancer immunotherapy, which was further underscored by the scientific community that awarded of the Nobel Prize in Physiology or Medicine to the two researchers who identified CTLA-4 and PD-1 in 2018." (PMID 31191545, 2019). "However, it has been recently shown that PD-1 and CTLA-4 are significantly overexpressed by peripheral blood T lymphocytes in cancer-bearing dogs compared with in healthy controls and that PD-1 blockade enhances T-cell activation." (PMID 31262050, 2019). "Gene profiling and phenotypical studies in mice and humans with cancer have shown that exhausted T-cells upregulate CTLA-4 and PD-1, which may aid in the survival of cancer cells." (PMID 30975211, 2019). "Consequently, immune-checkpoint inhibitors, CTLA-4, PD-1 and PD-L1, have emerged as both important cancer biomarkers and targets for immunotherapy." (PMID 30975211, 2019).
cancer (continued). "Additional potential gene targets are identified that have more highly correlated expression with CD3E than PDCD1 (ranked #55) and CTLA4 (ranked #103) when we expanded the list of studied genes from our 40-candidate list to all genes known to be expressed in cancer." (PMID 31360302, 2019). "CTLA-4 expression on CD4 cells was increased with 190% in cancer patients before treatment compared to healthy controls, and RT induced a further strong and persistent increase in CTLA-4 expression (212% increase one month after RT compared to pre-treatment levels)." (PMID 31500214, 2019). "Immune checkpoint blockade (ICB) immunotherapy increases antitumor immunity by blocking cytotoxic-T-lymphocyte-associated protein 4 (CTLA-4) or programmed cell death protein 1 (PD-1)/programmed death-ligand 1 (PD-L1) and displays robust clinical responses in various cancers." (PMID 31214189, 2019). "The development of CPIs, especially CTLA-4 and PD-1/PD-L1 antagonists, not only catalyzed progress in immuno-oncology, but now offers key ingredients for maximizing the efficacy of therapeutic cancer vaccines." (PMID 30774998, 2019). "Cancer type and summary repertoire features for 22 individuals receiving CTLA-4 monotherapy." (PMID 31993050, 2019). "CTLA-4 immunotherapy has been tested in human cancers and showed variable efficacy." (PMID 31775909, 2019). "Preclinical data suggest that modulation of the microbiota could become a novel strategy for improving the efficacy of immune-based therapies for cancer, in particular checkpoint blockade approaches targeting the CTLA-4 and PD-1 pathways." (PMID 30995949, 2019). "Furthermore, the pharmacological blockade of PD-1/PDL-1 is mainly targeted towards PD-L1 expressing cancer cells, with less toxicity for patients in comparison to anti-CTLA-4 inhibitory antibody therapies, as has been reported in the case of advanced melanoma." (PMID 31331034, 2019). "Alternative methods of reactivating the anti-cancer immune response are being actively investigated, the most successful of which involve neutralizing antibodies targeting immune checkpoint inhibitors such as PD-1 and CTLA-4." (PMID 30809511, 2019). "Blocking the interactions of these separate from or in addition to CTLA-4 and PD-1 might be expected to increase the potential to abrogate T cell exhaustion and reveal anti-cancer immune function." (PMID 30761152, 2019). "As hypothesized based on their mechanism of action, combination of PD-1 and CTLA-4 blockers has been successful in increasing the response rates and median survival time in cancer patients." (PMID 31196207, 2019). "The antagonistic mAbs used in immune checkpoint blockade are able to block T cell-inhibitory signaling from receptors such as cytotoxic T-lymphocyte-associated antigen 4 (CTLA-4) and programmed cell death-1 (PD-1), and have been successfully used in the treatment of several types of cancers." (PMID 31417564, 2019). "On the contrary, in our other studies we found significant differences between both lungs: the proportions of T regulatory cells (Tregs), CTLA-4+ Tregs, and M2 macrophages were higher in the lung affected by cancer when compared with the ‘healthy’ lung and correlated with advanced disease." (PMID 31010080, 2019). "Anti-CTLA-4 mAbs in combination with cancer vaccines have been tested in some preclinical studies." (PMID 30923527, 2019). "Different types of cancer immune checkpoint inhibitors have been approved recently: CTLA-4 monoclonal antibodies (as ipilimumab); anti-PD-1 monoclonal antibodies (as pembrolizumab and nivolumab); and anti-PD-L1 monoclonal antibodies (as atezolizumab, avelumab, and durmalumab)." (PMID 31137683, 2019). "ICIs play a pivotal role in the treatment of various advanced-stage cancers, as evidenced by monoclonal antibodies blocking the programmed cell death protein 1/programmed cell death 1 ligand 1 (PD-1/PD-L1) and the cytotoxic T-lymphocyte antigen-4 (CTLA-4)." (PMID 32010123, 2019).
cancer (continued). "Overall, these data support promising clinical possibilities of L. acidophilus lysates with CTLA-4 mAb in cancer patients and the hypothesis that probiotics help shape the anticancer immune response." (PMID 31882868, 2019). "This same patient population also expresses higher levels of PD-1 on their CD4+ T cells when compared to those of healthy controls and this is associated with T cell exhaustion; further, similar to CTLA-4, PD-1 levels are also related to HIV viral load and cancer progression." (PMID 31113482, 2019). "The previous efforts had largely focused on CTLA4 and PD-1 immune checkpoint blockades while the other T-cell coinhibitory/costimulatory molecules had not been well understood in terms of their roles in cancer biology." (PMID 31358815, 2019). "CTLA-4 molecules, which may be related to the occurrence and development of various malignant tumors, are involved in the negative regulation of the immune response, and their inhibitors (e.g., ipilimumab) have been explored as immune checkpoint drugs." (PMID 31462894, 2019). "For example, researchers have developed monoclonal antibody therapies that target programmed cell death protein-1 (PD-1), cytotoxic T lymphocyte-associated antigen-4 (CTLA-4), and indoleamine 2,3-dioxygenase (IDO) as reliable checkpoint molecules for cancer immunotherapy." (PMID 29721184, 2018). "Over the last few years, antibodies directed against CTLA-4, PD-1, and PD-L1 have shown promising antitumor activities in different cancer types, and the Food and Drug Administration (FDA) approved their use in patients affected by metastatic melanoma and lung cancer." (PMID 30123257, 2018). "Cancer immunotherapy represents a major breakthrough in cancer treatment with the emergence of immune-checkpoint inhibitors such as anti- programmed death 1 (PD-1) and anti- cytotoxic T lymphocyte antigen 4 (CTLA4)." (PMID 29969453, 2018). "Once the CTLA-4 signal was shown to restrict the activity of T cells, agents that shut down this signaling molecule became candidates for combination treatment with existing cancer therapeutics." (PMID 30135516, 2018). "This is illustrated by the involvement of the CTLA4 in both cancer and PIDs." (PMID 30443258, 2018). "Anti-CTLA-4 and anti-PD-1/PD-L1 therapy are the two main cancer treatments for ICB." (PMID 32793247, 2018). "Therefore, we investigated the ability of a-CTLA4-TGFβRII to elicit antitumor immunity and inhibit the growth and metastases of cancers that are refractory to current checkpoint inhibitors, such as TNBC." (PMID 29467463, 2018). "As in every cancer, targeting of CTLA-4 in AML or MDS requires the presence of functional T cells." (PMID 29868474, 2018). "The microRNA34/GAS6–Axl axis may resemble the PDL1/PD1 or CTLA‐4/B7 pathways in the mechanism by which they regulate the balance between immunosuppression (cancer) and immunostimulation (autoimmunity)." (PMID 29315512, 2018). "Following the success of anti-CTLA-4 therapy, antibodies targeting programmed cell death protein 1 (PD-1), or its ligand PD-L1, proved to be effective at improving overall survival in a wide variety of cancers." (PMID 30627131, 2018). "The cancer immunoediting process has been involved in the therapeutic effects of immunotherapies against cancer with immune checkpoint inhibitors such as CTLA-4, PD-L1, and PD-1 blockade, which target tumor escape mechanisms to reverse host immunosuppressive state." (PMID 29371832, 2018). "Other immune signatures of cancer immune status, namely PD-1, PD-L1, CTLA4, T cell immunoglobulin and mucin domain 3 (Tim3), IDO and IL-10, that potentially could be used as biomarkers of NACT response were analyzed in the pre-treatment biopsies." (PMID 30555458, 2018).
cancer (continued). "Although we still do not know how these pathways play Treg-specific roles, we do know that blocking these co-inhibitory pathways using anti-PD1 and anti-CTLA-4 antibodies promotes anti-cancer activity; such blocking antibodies are used widely for cancer treatment." (PMID 29510522, 2018). "With checkpoint inhibitors in cancer we have seen that combination blockade of both CTLA4 and PD1 is superior to either alone, and similarly we may expect that combining agonists against multiple pathways may enhance immunosuppression." (PMID 30349540, 2018). "As specific bacterium promotes cancer regression during CTLA-4 and PD-1 checkpoint blockades, a CD5 blockade in conjunction with bacterial selection may also improve immune response." (PMID 29701673, 2018). "The third phase (escape phase) begins when cancer cells become capable of binding and activating the co-inhibitory molecules on the T lymphocytes (CTLA-4, PD-1, LAG-3, TIM-3), and secreting soluble immunosuppressive or inducing the secretion of mediators such as IDO, TGFβ, IL10." (PMID 29492219, 2018). "Since these initial trials checkpoint inhibitors have gone on to show efficacy in a wide range of other cancers and whilst the list of indications for CTLA4 and PD1 blockade is growing, other immune inhibitory receptors are being investigated as potential targets in cancer therapy." (PMID 30349540, 2018). "Furthermore, additional studies in cancer patients show that after targeting CTLA-4 with ipilimumab, responding patients have increased ICOS + T cells." (PMID 29520282, 2018). "Another key prediction of the checkpoint blockade hypothesis is that anti-CTLA-4 mAb releases breaks of naive T cells to achieve cancer immunotherapeutic effect." (PMID 29472691, 2018). "This amounts to a cancer prevalence of 12.9% in patients with CTLA-4 insufficiency in our cohort." (PMID 30250467, 2018). "Most immunotherapies utilize antibodies to modulate immunity and in particular, antibodies against the co-inhibitory receptors cytotoxic T-lymphocyte associated antigen-4 (CTLA-4) and PD-1 have been approved by the FDA for treatment of several cancers due to their exceptional efficacy." (PMID 30631323, 2018). "In addition, other studies support the role of Bifidobacterium, Bacteroides, Faecalibacterium and Akkermansia species in cancer therapy targeting the immune checkpoint blockade (CTLA-4, PD-1), showing a T cell-specific anti-tumor-induced response." (PMID 30728820, 2018). "Indeed, the discovery of both cellular and molecular mechanisms of cancer immune evasion fuels the development of IO agents, including immune checkpoint blockers against CTLA4, PD-1, and PD-L1." (PMID 30577797, 2018). "However, with the recent entrance of the newest arsenal in the war on Cancer: anti- CTLA-4 and PD-1 checkpoint inhibitors have now taken the molecular oncology arena by storm." (PMID 29644213, 2018). "Thus, modulating CTLA-4 signaling is an attractive target for immunotherapies that seek to boost or impair early TCR signaling for cancer and autoinflammatory diseases." (PMID 29701673, 2018). "The discovery that immunoregulatory molecules such as PD-1 and CTLA-4 are amenable to therapeutic manipulation by antibodies that block these signaling pathways has revolutionized cancer immunotherapy, and is a potential avenue for novel approaches in the treatment of infectious diseases." (PMID 30233588, 2018). "CTLA-4 on CD4+ Tregs is an additional mechanism of immune suppression in cancer." (PMID 30108594, 2018). "Further research will address whether combining anti-CTLA-4 and anti-PD-1 antibodies will improve cancer treatments." (PMID 29701673, 2018). "While CTLA-4 blockade has been shown to selectively deplete Tregs in a Fc-Fcγ-dependent manner in mouse models, it is unable to deplete Tregs in human cancers, highlighting the need and potential for modifications of Fc portions for enhanced Fc-mediated depletion of Tregs." (PMID 30360504, 2018).